LPL (lipoprotein lipase)
Diseases named in the same sentence as LPL in open-access papers (continued):
Sharing a sentence is not in itself a finding about the gene and the disease.
hypertriglyceridemia (continued). "Familial hypertriglyceridemia is the result of a single gene mutation, usually in the lipoprotein lipase (LPL) or ApoC2 or ApoA5 genes involved in TG metabolism, and manifests as severe hypertriglyceridemia (TG > 10 mmol/L) with an incidence of about 1 in 1 million." (PMID 37711173, 2023). "Hypertriglyceridemia may be caused by a decrease in lipoprotein lipase activity combined with an increase in hormone-sensitive lipase activity, resulting in decreased TG uptake from the circulation." (PMID 36977218, 2023). "It suggests that the modulation of these LPL regulators could offer a therapeutic treatment for hypertriglyceridemia and reduce the risk for related heart disease." (PMID 37233656, 2023). "The important role that apoCIII plays as an LPL inhibitor as well as the findings from studies on animal and human loss of function have also shown the potential use of apoCIII inhibitors as a treatment approach for hypertriglyceridemia." (PMID 38303975, 2023). "Therefore, defective LPL can cause severe hypertriglyceridemia, such as type I hyperlipoproteinemia, a rare autosomal recessive genetic disease." (PMID 35923617, 2022). "Thus far, only one drug was registered for the treatment of severe hypertriglyceridemia which concerns gene therapy for patients suffering from lipoprotein lipase (LPL) deficiency." (PMID 35107764, 2022). "For example, of the 25 different lower frequency variants we detected in LPL in 36 individuals, 69% had hypertriglyceridemia, of which most (n = 22) had levels >10 mmol/L or the clinical indication of hypertriglyceridemia, and three had levels between 5 and 10 mmol/L." (PMID 34440342, 2021). "The GWASs performed thus far have implicated several genes already known to be involved in monogenic and familial hypertriglyceridemias, identifying associations of common variants proximal to LPL, APOE, APOC2, and the APOA1-C3-A4-A5 cluster with triglyceride levels [23••]." (PMID 34146174, 2021). "Consequently, mutations in LPL and GPIHBP1 are associated with hypertriglyceridemia as a result of impaired LPL-mediated TG hydrolysis." (PMID 34801488, 2021). "Deckert et al29 proposed that in microalbuminuria, endothelial cell damage causes a lowering of lipoprotein lipase levels at the endothelium, leading to widespread vascular damage, causing an increase in the concentration of plasma triglycerides leading to hypertriglyceridaemia." (PMID 33532603, 2021). "Genetic loss- or gain-of-function of LPL in animal models and in humans has demonstrated the key role it plays in TG clearance, with genetic loss-of-function in LPL or key adaptors leading to severe hypertriglyceridemia." (PMID 34543263, 2021). "This binding pose aligns well with data from HDX-MS analyses and site-directed mutagenesis —and it explains why certain genetic variants of GPIHBP1 and LPL are associated with hypertriglyceridemia as they compromise the complementarity of the binding interface." (PMID 34336854, 2021). "Recently, mounting evidence has shown that increased LPL activity can promote the clearance of plasma TG; however, LPL deficiency or loss of its enzymatic activity leads to TG accumulation in the plasma, causing hypertriglyceridemia." (PMID 34576019, 2021). "Nevertheless, targeting LPL with miR-27a-3p might have important implications in diseases associated with decreased LPL function, such as hypertriglyceridemia." (PMID 34831427, 2021). "In addition, L279V mutation in the LPL gene and a reported mutation (A98T) compound heterozygote were proven to inhibit LPL enzymatic activity and lead to severe hypertriglyceridemia and acute pancreatitis." (PMID 34485189, 2021). "Furthermore, there is no such thing as autosomal dominant hypertriglyceridemia: within the same family, carriers of heterozygous LPL variants have biochemical phenotypes ranging from completely normal to severe hypertriglyceridemia." (PMID 32793115, 2020).
hypertriglyceridemia (continued). "As a result, mutations in GPIHBP1 or LPL can lead to severe hypertriglyceridemia." (PMID 32504883, 2020). "Volanesorsen is being developed for reduction of triglyceride levels in patients with familial chylomicronemia syndrome (FCS), a rare autosomal recessive disorder characterized by severe hypertriglyceridemia and recurrent pancreatitis due to a deficiency in LPL or associated proteins." (PMID 32589506, 2020). "The proposed mechanism is based on two points: first, the concentrations of chylomicron and LDL-C are increased due to insulin deficiency in T1D, and second, decreasing the activity of lipoprotein lipase in T1D condition which eventually leads to hypertriglyceridemia." (PMID 32695298, 2020). "However, definite proof that RLPs rather than nascent TRLs are the cause of greater CVD in patients with hypertriglyceridemia and/or defects in genes leading to reduced LPL actions is still missing and will require further research." (PMID 32849290, 2020). "Additionally, a reduced lipoprotein lipase enzyme activity and insulin resistance leads to decrease in lipid catabolism at the tissue level which causes hypertriglyceridemia." (PMID 33362205, 2020). "LPL mutation was detected in 8 (25.8%) of the 31 hypertriglyceridemia cases." (PMID 31203594, 2019). "It is suggested that hypertriglyceridemia may be caused by SGAs through stimulation of hepatic triglyceride production and secretion or through inhibition of lipoprotein lipase-mediated triglyceride hydrolysis." (PMID 31736812, 2019). "Removal of LPL by Cre during skeletal and cardiac muscle development does not mimic LPL deficiencies in human patients, however, the mouse provides an improved system than those previously available for testing alternative gene therapies to reduce hypertriglyceridemia associated with LPL deficiency." (PMID 29304082, 2018). "Thus, we developed a new mouse model for LPL deficiency that exhibits hypertriglyceridemia and significantly reduced striated muscle LPL activity by employing a striated muscle specific Cre driver to conditionally knockout striated muscle LPL." (PMID 29304082, 2018). "It is speculated that the increased hydrolysis of maternal TG by placental lipoprotein lipase to FFAs and the excessive delivery of fatty acids to the fetus may be partly responsible for the increased risk of macrosomia among women with hypertriglyceridemia." (PMID 29642923, 2018). "Deficient LPL could dramatically increase CM levels and become a high-risk factor for acute pancreatitis, hypertriglyceridemia, diabetes mellitus, and other metabolic disorders." (PMID 29921298, 2018). "Two heterozygous LPL SNPs, W14X and L279 V, were newly found to be compound but dislinked, which may cause long-term severe hypertriglyceridemia and recurrent acute pancreatitis." (PMID 29921298, 2018). "To develop a tractable model to test rescuing LPL deficiencies in adult mice we asked if knocking out LPL in differentiated striated (skeletal and cardiac) muscle using a muscle creatine kinase (mck) Cre would cause both hypertriglyceridemia and lower post-heparin plasma LPL activity." (PMID 29304082, 2018). "Nevertheless the existence of predisposing factors for hypertriglyceridemia such as Asn9 variant of lipoprotein lipase discovered in a brotherhood among patients should remind the probable role for other genes in the pathogenicity of the different symptoms observed in the disease." (PMID 28057010, 2017). "In the presence of certain LPL mutations (e.g., mutations in the catalytic triad or mutations that prevent LPL dimerization), the processing of TRLs is markedly impaired, leading to severe hypertriglyceridemia (familial chylomicronemia)." (PMID 26725083, 2016). "The discovery of Angptl8 seems to complete the player set for LPL regulation, but it is puzzling that all the three Angptl members are LPL inhibitors, and that deficiency (overexpression) of any one of them results in hypotriglyceridaemia (hypertriglyceridaemia)." (PMID 27053679, 2016).
hypertriglyceridemia (continued). "In both humans and mice, deficiency of LPL results in severe hypertriglyceridaemia." (PMID 27053679, 2016). "Thus, these gain-of-function and loss-of-function experiments revealed the involvement of LPL in the mechanism of hypertriglyceridemia observed in Rheb mice." (PMID 26268630, 2015). "LPL gene mutations contribute to the hypertriglyceridemia observed in T2DM patients." (PMID 25924608, 2015). "The complete loss of LPL activity significantly decreases the clearance of CM-TG, leading to CM accumulation in both the fed and fasted states (i.e. chylomicronemia), and severe hypertriglyceridemia." (PMID 25889044, 2015). "Indeed, LMF1-/- pups exhibit hypertriglyceridemia and severely diminished post-heparin LPL and HL activities, hallmark features of LMF1 deficiency in the cld mouse model." (PMID 25302068, 2014). "Alterations or mutations in the LPL gene could result in massive accumulation of chylomicrons and profound fasting hypertriglyceridemia (HTG)." (PMID 24646025, 2014). "In both mice and humans, loss-of-function mutations in LPL result in severe hypertriglyceridemia." (PMID 25212743, 2014). "Similarly, loss-of-function mutations in GPIHBP1, which is required for proper targeting of LPL to the lumen of capillaries, also cause hypertriglyceridemia." (PMID 25212743, 2014). "It has been shown that defective LPL can cause hypertriglyceridemia." (PMID 24086538, 2013). "Similarly, ApoC2 functions as cofactor in LPL-mediated TG hydrolysis and ApoC2 deficiency in humans is associated with severe hypertriglyceridemia." (PMID 23469003, 2013). "Hypertriglyceridaemia is one of the important risk factors of acute pancreatitis and recurrent pancreatitis is common in patients with severe hypertriglyceridaemia caused by mutations in lipoprotein lipase or apolipoprotein CII." (PMID 23028532, 2012). "Indeed, VLDL-R-deficient mice have reduced LPL activity because the VLDL receptor is involved in the translocation of LPL from cardiomyocytes to the endothelial surface, causing hypertriglyceridaemia associated with reduced catabolism of VLDL-TAG by LPL." (PMID 21773049, 2011). "Loss-of-function mutations in APOC2 and LPL are associated with severe hypertriglyceridemia." (PMID 19878569, 2009). "Perturbation in LPL activity could therefore lead to significant metabolic consequences and LPL has been implicated in pathophysiological conditions characterized by marked hypertriglyceridaemia, such as that observed in the metabolic syndrome (MetS)." (PMID 19638239, 2009). "Although heparin can boost LpL activity to facilitate TG metabolism, both the Endocrine Society and American Association of Clinical Endocrinologists recommended against its use due to the risk of bleeding, hemorrhagic pancreatitis, and rebound hypertriglyceridemia." (PMID 39949380, 2025). "Additionally, hypertriglyceridaemia is caused by the decreased activity of lipoprotein lipase." (PMID 40261481, 2025). "Genetic deletion of ApoC2 impairs the ability of LPL to break down lipoproteins that are rich in triglycerides, resulting in a significant increase in plasma triglyceride levels and eventually causing severe hypertriglyceridemia and spontaneous atherosclerosis." (PMID 39798876, 2025). "Therefore, a large genetic study across many populations, especially on H+H+ LPL-Hind lll polymorphism as a genetic marker of susceptibility to severe hypertriglyceridemia, may be of great importance." (PMID 37954769, 2023). "The important role that apoCIII plays as an LPL inhibitor as well as the findings from studies on animal and human loss of function have also shown the potential use of apoCIII inhibitors as a treatment approach for hypertriglyceridemia, as we summarize in section." (PMID 38303975, 2023). "In addition, obesity may cause hypertriglyceridemia by decreasing the expression of lipoprotein lipase (LPL) mRNA and reducing the lipolytic capacity of triglyceride-rich lipoproteins." (PMID 34948819, 2021).
hypertriglyceridemia (continued). "Hence, LPL deficiency is responsible for hypertriglyceridemia." (PMID 32549042, 2020). "Also, in the case of this animal model, a low activity of LPL could be one of the causes of hypertriglyceridemia, activity of this enzyme in the liver being only 20% and 30%, respectively, of the values in C57BL mice and F344 rats." (PMID 22028972, 2012). "Therefore, we chose LPL deficient (LPL-/-) mice with severe hypertriglyceridemia as an alternative model to assess the role of macrophage LPL in plasma lipoprotein metabolism via bone marrow transplant, through which LPL will be produced mainly by hematopoietic cell-derived macrophages." (PMID 21980507, 2011). "We therefore studied LPL mass and activity, hepatic lipase activity, the levels of apolipoprotein C-II and apo E and apo A-V polymorphisms in order to detect any differences between persons with hypertriglyceridaemia who developed hypertriglyceridaemic pancreatitis and those who did not." (PMID 19534808, 2009). "Another limitation of this study was that our infusions included heparin, which stimulates release of lipoprotein lipase and reduces likelihood of hypertriglyceridemia." (PMID 40857742, 2025). "Laboratory findings include severe hypertriglyceridemia, sometimes >1000 mg/dl, the milky appearance of fresh plasma, low apolipoprotein B levels, and low levels of post-heparin-plasma LPL activity." (PMID 41180755, 2025). "Impaired LPL activity results in hypertriglyceridemia and elevated pre-beta fractions, as observed in this study." (PMID 39858256, 2025). "Insulin deficiency in diabetes can result in hypertriglyceridemia (HTG), as insulin is an anti-lipolytic agent and regulator of lipoprotein lipase (LPL) enzyme actions." (PMID 40612706, 2025). "Familial chylomicronemia syndrome (FCS) is a rare autosomal recessive disorder characterized by severe hypertriglyceridemia due to impaired lipoprotein lipase (LPL) function." (PMID 41180755, 2025). "This case of severe hypertriglyceridemia with pseudohypocalcemia illustrates the combined effects of insulin resistance and dysfunctional LPL activity." (PMID 41393592, 2025). "Insulin plays a pivotal role in managing severe hypertriglyceridemia by activating lipoprotein lipase (LPL), which facilitates the breakdown of triglycerides into free fatty acids." (PMID 39958046, 2025). "When the acidic tail was neutralized in gene-edited mice, LPL remained trapped in the sub-endothelial spaces triggering hypertriglyceridemia." (PMID 39814316, 2025). "With the use of an oral lipid challenge, we discovered that a single dose of acyl-GIP blunts hypertriglyceridemia through mechanisms of plasma lipid clearance into BAT via increases in lipoprotein lipase (LPL) activity." (PMID 40983752, 2025). "Glycosylphosphatidylinositol-anchored high-density lipoprotein-binding protein 1 (GPIHBP1) is an anchor protein of LPL in the vascular endothelium, and autoantibodies against GPIHBP1 can decrease the LPL activity levels to cause hypertriglyceridemia." (PMID 41156460, 2025). "Previous studies have demonstrated that this hypertriglyceridemia is likely due to the inhibition of lipoprotein lipase (LPL) activity and the overproduction of VLDL." (PMID 41195480, 2025). "Simultaneously, IFN-γ and TNF-α (tumor necrosis factor alpha) inhibit lipoprotein lipase, contributing to hypertriglyceridemia." (PMID 41148945, 2025). "Estrogen mediates this protection by enhancing adipose lipoprotein lipase (LPL) activity to promote TG hydrolysis and lipoprotein clearance, while HFD suppresses adipose LPL activity in males, exacerbating hypertriglyceridemia." (PMID 40429918, 2025). "Apolipoprotein C-III (apoC3) and angiopoietin-like protein 8 (ANGPTL8), recognized as inhibitors of lipoprotein lipase, play a role in modulating hypertriglyceridemia." (PMID 39944202, 2025).
hypertriglyceridemia (continued). "Bi-allelic loss-of-function variants in LPL or in other genes promoting LPL activity in the capillary lumen (e.g., APOC2, APOA5, LMF1, GPIHBP1) cause severe hypertriglyceridemia with a predisposition to acute pancreatitis." (PMID 39814316, 2025). "The importance of LPL and GPIHBP1 for plasma TG catabolism in humans is evidenced by the fact that a genetic deficiency in either protein causes a condition of hypertriglyceridemia known as familial chylomicronemia syndrome (FCS)." (PMID 40100923, 2025). "Some cases of severe hypertriglyceridemia have been suggested to have a digenic origin, involving mutations in both LMF1 and LPL." (PMID 40142634, 2025). "Heparin, when used in combination with insulin, releases stored LPL to reduce triglyceride levels but carries risks such as rebound hypertriglyceridemia and hemorrhage with continuous use." (PMID 40432658, 2025). "LPL dysfunction can lead to hypertriglyceridemia and, subsequently, the development of atherosclerosis." (PMID 39590382, 2024). "Insulin resistance induced by dietary sodium restriction reduces lipoprotein lipase enzyme expression and activity, impairing TG-rich plasma LP (chylomicron and very low-density lipoprotein) metabolism and favoring hypertriglyceridemia." (PMID 39337664, 2024). "When chickens were given an intravenous injection of an inhibitory LPL-specific antibody, TG clearance from the plasma was nearly abolished, resulting in severe hypertriglyceridemia." (PMID 39435661, 2024). "TNF also affects the lipid metabolism and hypertriglyceridemia by decreasing lipoprotein lipase activity in adipocytes." (PMID 38396488, 2024). "Recombinant MIF infusion restored high plasma MIF levels in Par2–/– mice, and the levels decreased LPL and attenuated adipocyte lipid storage, leading to hypertriglyceridemia." (PMID 38973609, 2024). "Our clinical data demonstrate that obesity upregulates PAR2 expression in WAT, which inversely correlates with LPL gene expression, leading to hypertriglyceridemia." (PMID 38973609, 2024). "Our current study identifies a regulatory mechanism of LPL in WAT which contributes to hypertriglyceridemia." (PMID 38973609, 2024). "Elevated PAR2 gene expression is associated with reduced LPL expression in WAT and hypertriglyceridemia following high palmitic acid diet feeding." (PMID 38973609, 2024). "MIF overexpression induces high-circulating MIF levels, thereby suppressing adipose LPL and inducing hypertriglyceridemia." (PMID 38973609, 2024). "This deficiency leads to impaired activation of LPL, and individuals with APOC2 deficiency experience severe hypertriglyceridemia." (PMID 38521668, 2024). "In mice, cats, and humans, LPL deficiency markedly impairs TRL processing, resulting in severe hypertriglyceridemia (chylomicronemia)." (PMID 39435661, 2024). "Restoration of high plasma MIF levels reverses high LPL in WAT of PAR2-deficient mice, resulting in hypertriglyceridemia." (PMID 38973609, 2024). "Recent findings also indicated that MIF directly inhibits the expression and activity of lipoprotein lipase (LPL) in mouse adipose tissue, thereby impairing LPL’s ability to break down plasma TG, resulting in hypertriglyceridemia." (PMID 38802393, 2024). "Transgenic defects in LPL in adipose tissue are associated with elevated plasma TG levels, suggesting a critical role for adipose LPL in regulating hypertriglyceridemia." (PMID 38973609, 2024). "Later in vivo studies demonstrated that the hypertriglyceridemia in APOA5 KO mice results from decreased intracapillary LPL amounts in oxidative tissues and that an anti-A3/8 antibody normalizes circulating TG concentrations in these mice." (PMID 38521668, 2024).